ZFPM1 (zinc finger protein, FOG family member 1)
Description:
Transcription regulator that plays an essential role in erythroid and megakaryocytic cell differentiation. Essential cofactor that acts via the formation of a heterodimer with transcription factors of the GATA family GATA1, GATA2 and GATA3. Such heterodimer can both activate or repress transcriptional activity, depending on the cell and promoter context. The heterodimer formed with GATA proteins is essential to activate expression of genes such as NFE2, ITGA2B, alpha- and beta-globin, while it represses expression of KLF1. May be involved in regulation of some genes in gonads. May also be involved in cardiac development, in a non-redundant way with ZFPM2/FOG2 (By similarity).
Synonyms: FOG1; PRDM18; FOG; ZNF89A; ZC2HC11A
Tractability: No criterion of Open Targets' tractability assessment is met for any kind of drug.
Gene: Protein-coding gene on chromosome 16 (88,453,280 to 88,537,031, forward strand). Ensembl gene ENSG00000179588.
Subcellular location: Nucleus
Subcellular location (Human Protein Atlas): Nucleoplasm
Pathways (Reactome):
Gene expression (Transcription): RUNX1 regulates genes involved in megakaryocyte differentiation and platelet function
Hemostasis: Factors involved in megakaryocyte development and platelet production
Gene Ontology:
Molecular function: protein binding; RNA polymerase II-specific DNA-binding transcription factor binding; transcription corepressor activity
Biological process: negative regulation of interleukin-4 production; negative regulation of transcription by RNA polymerase II; platelet formation; positive regulation of type II interferon production; regulation of definitive erythrocyte differentiation; atrial septum morphogenesis; atrioventricular valve morphogenesis; cardiac muscle tissue morphogenesis; embryonic hemopoiesis; erythrocyte differentiation; heart development; megakaryocyte differentiation; mitral valve formation; negative regulation of mast cell differentiation; outflow tract morphogenesis; positive regulation of transcription by RNA polymerase II; T-helper cell lineage commitment; tricuspid valve formation; ventricular septum morphogenesis; anatomical structure formation involved in morphogenesis; immune system process; leukocyte differentiation; myeloid cell differentiation; negative regulation of multicellular organismal process; regulation of cytokine production; and 2 more
Cellular component: transcription regulator complex; transcription repressor complex; chromatin; nucleoplasm; nucleus
Genetic constraint (gnomAD): Loss-of-function variants: 29 observed, 35.51 expected, observed/expected ratio (o/e) 0.82, 90% interval 0.61 to 1.11. The synonymous counts are far from expectation, so gnomAD's model fits this gene poorly and the ratio says little. Missense variants: 1,814 observed, 1,075 expected, observed/expected ratio (o/e) 1.69, 90% interval 1.62 to 1.75. Synonymous variants: 923 observed, 531.42 expected, observed/expected ratio (o/e) 1.74, 90% interval 1.64 to 1.83.
Gene-disease validity (ClinGen):
ClinGen rates the evidence that ZFPM1 causes each of these diseases.
congenital heart disease (autosomal dominant): Limited. A heart disease that is present at birth.
Homologues: Orthologues: macaque ZFPM1 (94% identical), chimpanzee ZFPM1 (94% identical), dog ZFPM1 (75% identical), rat Zfpm1 (74% identical), mouse Zfpm1 (74% identical), pig ZFPM1 (68% identical), guinea pig ZFPM1 (62% identical), tropical clawed frog zfpm1 (50% identical), zebrafish zfpm1 (47% identical), Drosophila melanogaster ush (20% identical). Paralogues in human: ZFPM2 (32% identical).
Diseases named in the same sentence as ZFPM1 in open-access papers:
ZFPM1 is named in the same sentence as 41 diseases in open-access papers, as found by Europe PMC text mining. Sharing a sentence is not in itself a finding about the gene and the disease. The quoted sentences say what the papers report.
anemia (7 papers, 2009 to 2025). A reduction in the number of red blood cells, the amount of hemoglobin, and/or the volume of packed red blood cells. "Similar to the Gata1 knockout phenotype, deletion of the Zfpm1 gene in mice resulted in embryonic lethality between embryonic days 10.5 to 12.5, due to severe anemia." (PMID 40048486, 2025). "In a murine Trypanosoma congolense infection model, mice exhibiting decreased ZFPM1 expression recovered more effectively from anaemia." (PMID 38571912, 2024). "The transcription factors Tal1, Gata1, Lmo2 and Fog1 (Zfpm1) all had lower expression in C57BL/6 than BALB/c consistent with more severe anaemia in C57BL/6." (PMID 19365556, 2009). "The knockout of the Zfpm1 gene, coding for FOG-1, results in early embryonic lethality due to anemia in mice, similar to the embryonic lethal phenotype of the Gata1 gene knockout." (PMID 40048486, 2025). "Several transcription factors regulating haematopoiesis, Tal1, Gata1, Zfpm1 and Klf1 were expressed at consistently lower levels in C57BL/6 mice suggesting that these mice have a lower haematopoietic capacity and therefore less ability to recover from haemolysis induced anaemia after infection." (PMID 19365556, 2009).
asthma (5 papers, 2015 to 2024). "In the unadjusted model of current wheeze, the CpG site with the strong association (cg12077460) mapped to the MFHAS1 gene, whereas the top association in current asthma mapped to ZFPM1 (cg04983687)." (PMID 29046734, 2017). "Also, two differentially methylated regions in ZFPM1 were recently identified in association with asthma." (PMID 26292806, 2015). "DNA methylation in CpGs annotated to the ZFPM1 (cg04983687, cg08940169) and ACOT7 (cg09249800, cg21220721, cg11699125) genes were also shown to be strongly associated in the asthma study and in our analysis focusing on ADEH+." (PMID 31443688, 2019). "Functional gene categories represented in DMRs and individual CpGs found for FeNO, asthma, and allergy were eosinophilic activity (EPX, CLC, PRG2), and Th2 responses (IL-4, ZFPM1)." (PMID 31300640, 2019). "The ZFPM1 gene known to facilitate Th1 differentiation through the downregulation of the Th2 cytokine IL-420 had lower DNAm levels for participants with higher levels of FeNO (DMR), total IgE, environment IgE sensitization, asthma, and allergic asthma." (PMID 31300640, 2019). "The top locus associated with current asthma at 7.5 years adjusted for cell counts that did not include eosinophils and neutrophils mapped to ZFPM1 (cg04983687) with a − 5.02 [95% CI − 3.5, − 6.5] difference in percentage methylation for individuals with asthma." (PMID 29046734, 2017).
Thrombocytopenia (5 papers, 2012 to 2021). A reduction in the number of circulating thrombocytes. "ZFPM1 seems also to be crucial for correct bone marrow function as deletion for this gene seems to result in (asymptomatic) thrombocytopenia with reduced penetrance." (PMID 28422132, 2017). "Similarly, the lens defect found in our patient 1, whose deletion breakpoint falls at 41 kb downstream to the 3′ of ZFPM1, may be explained in term of disruption of regulatory elements of the gene, as already hypothesized above for thrombocytopenia." (PMID 28422132, 2017).
breast carcinoma (4 papers, 2019 to 2024). "In addition, SPI1 and another proposed pleiotropic factor, ZFPM1/FOG1 (which is linked to BRCA1-associated breast cancer and eosinophil counts, among other blood traits), are involved in the lineage commitment of eosinophils." (PMID 38308367, 2024). "In addition, in our tumour type-specific analyses, we identified a metastatic breast cancer-specific significantly mutated gene—ZFPM1 (also known as FOG1; q = 8 × 10−5), a zinc-finger transcription factor protein without clear links to cancer." (PMID 31645765, 2019). "Predictions of known cancer driver genes in new cancer types include SPTA1, CHD4 and ASXL1 in colorectal cancer, FOXO3, MUC16 and ZFPM1 in breast cancers and CNTNAP2, CTNND2 and TRRAP in lung adenocarcinoma." (PMID 38890488, 2024). "Of the chromatin modification genes, ZFPM1 gene was found to be the most frequently mutated in EPCs, and the mutation of ZFPM1 gene had not been reported in other breast cancer studies." (PMID 34007008, 2021). "Among these recurrent mutated genes, ZFPM1 gene mutations have not been reported in breast cancer." (PMID 34007008, 2021). "To date, ZFPM1 mutations have not been described in breast cancer studies." (PMID 34007008, 2021).
allergic asthma (3 papers, 2019 to 2024). A asthma with a basis in a pathological type I hypersensitivity reaction. "The genes associated with mucin production (GAL3ST2), leukotriene synthesis (GPX4), Th2-mediated allergic asthma (PTBP1, ZFPM1, SBNO2, and EGFL7), and IgE mediated allergy (PAK2) were also represented in our polygenic prediction models of ICS response." (PMID 38540988, 2024).
allergic disease (3 papers, 2015 to 2024). An immune response that occurs following re-exposure to an innocuous antigen, and that requires the presence of existing antibodies against that antigen. "The multifaceted roles of ZFPM1 in immune-cell activity and allergic disease suggest that this is an interesting yet possibly overlooked gene in atopy and atopic diseases." (PMID 26292806, 2015).
leukemia (3 papers, 2011 to 2018). A malignant (clonal) hematologic disorder, involving hematopoietic stem cells and characterized by the presence of primitive or atypical myeloid or lymphoid cells in the bone marrow and the blood. "Reduced expression of ZFPM1/FOG1 was found in preleukemic progenitors of a mouse model of leukemia." (PMID 30347759, 2018).
adrenocortical carcinoma (2 papers, 2018 to 2020). "Of note, ZFPM1/FOG1 mutations occurred in 50% of adrenocortical carcinoma patients and were localized in a hotspot region." (PMID 30347759, 2018).
Astigmatism (2 papers, 2017 to 2021). A type of refraction error associated with abnormal curvatures on the anterior and/or posterior surface of the cornea. "ZFPM1 is also crucial for correct eye development through the interaction with GATA factors, and its haploinsufficiency seems to be associated with severe astigmatism, what was presented in several patients." (PMID 34604130, 2021). "In this sense, the presence of severe astigmatism in patients 3 and 4 in Willemsen et al16 and in our cases 3 and 6 may be explained by an impairment of ZFPM1 function." (PMID 28422132, 2017). "ZFPM1 (FOG1) is also crucial for a correct eye development through the interaction with other GATA factors and its haploinsufficiency seems to be associated with severe astigmatism, as reported in our cases 1, 3, 6 and 7, and patients 3 and 4 in Willemsen et al16." (PMID 28422132, 2017).
psychosis (2 papers, 2019 to 2022). "One additional genetic locus previously linked to psychosis in Alzheimer’s disease, ZFPM1 (Chr16q24.2), showed suggestive association with DLB at p-value < 1 × 10−6." (PMID 31065058, 2019). "Of note, this site is annotated to the ZFPM1 gene that encodes a zinc finger protein that has been previously associated with DLB38 and psychosis in AD39." (PMID 36153390, 2022).
Anxiety (1 paper, 2024). Intense feelings of nervousness, tension, or panic often arise in response to interpersonal stresses. "Within the ZNF family, FEZ zinc finger 1 (FEZF1), FEZ zinc finger 2 (FEZF2), ZNF, and FOG family member 1 (ZFPM1) contribute to the development and function of neural circuits, which are crucial for fear, anxiety, and behavioral regulation." (PMID 39595393, 2024).
colon adenocarcinoma (1 paper, 2021). "The frequency of ZFPM1 mutations in our EPCs was also significantly higher than that in other tumor types according to the TCGA database, including colon adenocarcinoma, uterine corpus endometrial carcinoma, stomach adenocarcinoma, and invasive breast carcinoma (p < 0.05, Chi-square test)." (PMID 34007008, 2021).
invasive breast carcinoma (1 paper, 2021). A carcinoma that infiltrates the breast parenchyma. "In COSMIC database (tissue: breast; n = 2534), fifteen (0.59%, 15/2534) invasive breast carcinomas were found with ZFPM1 mutations." (PMID 34007008, 2021).
malaria (1 paper, 2022). Malaria is a serious and sometimes fatal disease caused by a parasite that commonly infects a certain type of mosquito which feeds on humans. "Upon infection with malaria, the expression of Zfpm1 was only slightly—if at all—changed during progression of infection in unvaccinated mice; only towards the end of the crisis phase on day 11 p.i., there was an increase in Zfpm1 expression." (PMID 35214745, 2022).
Obesity (1 paper, 2021). Accumulation of substantial excess body fat. "We further examined whether the diminished binding of CtBP2 observed in obesity is specific to FoxO1 and SREBP1 by detecting the interaction of CtBP2 with a known partner, zinc-finger protein FOG family member 1 (ZFPM1), that was again decreased in the liver of obesity (~96%)." (PMID 34728642, 2021).
tumor (8 papers, 2009 to 2023). "The frequency of ZFPM1 mutations in the EPCs was significantly higher than that of other tumor types." (PMID 34007008, 2021). "Somatic ZFPM1 mutations were identified by WES in six cases (6/26, 23.0%), and an additional 3 tumor samples with ZFPM1 mutations were revealed in 15 additional cases by TS." (PMID 34007008, 2021). "Heterogeneity in the mutation frequencies was observed in the different tumor types with higher mutation rates found for PRDM3/MECOM, PRDM8, PRDM9, PRDM15, ZFPM1/FOG1 and ZFPM2/FOG2 in specific cancers." (PMID 30347759, 2018). "We inferred that ZFPM1 might play a role as a potential tumor suppression gene in EPC, which should be further validated by copy number analysis in the region of ZFPM1 and functional assays." (PMID 34007008, 2021).
cancer (7 papers, 2014 to 2024). A tumor composed of atypical neoplastic, often pleomorphic cells that invade other tissues. "Otherwise, ZFPM1/FOG1 was mutated at a low rate in a few cancer types, except in UCS (5.2%), COAD (6.6%), READ (9.4%), and ACC (50.5%)." (PMID 30347759, 2018). "Indeed, our pan-cancer analysis revealed ZFPM1/FOG1 mutation occurrence in about 50% of ACC patients." (PMID 32290321, 2020). "We also detected another five smRMGs that mutated in nearly half of the samples in corresponding cancers, including PCDHAC2 in SKCM (53%), ZFPM1 in ACC (52%), VHL in KIRC (49%), GNAQ in UVM (49%), and ADAM6 in LUSC (45%)." (PMID 30107644, 2018). "Based on the scores of this analysis, ZFPM1/FOG1 can be considered as a cancer driver for ACC and PRDM8 for PAAD." (PMID 30347759, 2018). "Interestingly, ZFPM1/FOG1 revealed a high number of samples, especially in ACC, with “multi_hit” mutations (more than one mutation affecting the same gene in the same cancer sample)." (PMID 30347759, 2018). "In this study, OncodriveCLUST analysis revealed two putative cancer mut-driver genes: PRDM8 in PAAD and ZFPM1/FOG1 in ACC." (PMID 30347759, 2018). "In addition, ZFPM1 belongs to the positive regulatory domain (PRDM) gene family, which are involved in human cancer through modulation of several processes, such as epigenetic modifications and genetic reprogramming." (PMID 34007008, 2021). "Finally, an interesting finding from a GWAS meta-analysis reported both ZFPM1 and ZFPM2 as genes influencing the circulating levels of the angiogenic vascular endothelial growth factor (VEGF), which is known to impact various physiological and disease processes including cancer." (PMID 32290321, 2020).
blood disorders (3 papers, 2006 to 2020). "As expected from its function during hematopoiesis, several studies have shown a deregulation of ZFPM1 and its related pathway in hematologic malignancies." (PMID 32290321, 2020).
ZFPM1 also shares sentences with these, for which no sentence is quoted: infection (4 papers); Allergy (2); dementia (2); lymphoma (2); allergic respiratory disease (1); Alzheimer disease (1); bleeding disorders (1); Candidemia (1); Cognitive impairment (1); colorectal cancer (1); Dyskinesia (1); lung adenocarcinoma (1); lung carcinoma (1); melanoma (1); metastatic cancer (1); myeloma (1); neurological diseases (1); papillary carcinoma (1); Splenomegaly (1); stomach adenocarcinoma (1); urticaria (1); uterine corpus endometrial carcinoma (1); X-linked thrombocytopenia (1).